EHBP1L1 (EH domain binding protein 1 like 1)
Description:
May act as Rab effector protein and play a role in vesicle trafficking.
Synonyms: DKFZp762C186; TANGERIN
Tractability: Antibody: the Human Protein Atlas places it where antibodies can reach. PROTAC: ubiquitination databases record sites on it; its protein half-life has been measured.
Gene: Protein-coding gene on chromosome 11 (65,575,943 to 65,592,851, forward strand). Ensembl gene ENSG00000173442.
Subcellular location: Endosome
Subcellular location (Human Protein Atlas): Plasma membrane; Vesicles
Gene Ontology:
Molecular function: actin filament binding; small GTPase binding
Biological process: actin cytoskeleton organization; endocytic recycling
Cellular component: membrane; plasma membrane; endosome
Genetic constraint (gnomAD): Loss-of-function variants: 122 observed, 133.55 expected, observed/expected ratio (o/e) 0.91, 90% interval 0.79 to 1.06. The synonymous counts are far from expectation, so gnomAD's model fits this gene poorly and the ratio says little. Missense variants: 1,941 observed, 1,799.2 expected, observed/expected ratio (o/e) 1.08, 90% interval 1.04 to 1.12. Synonymous variants: 878 observed, 746.99 expected, observed/expected ratio (o/e) 1.18, 90% interval 1.11 to 1.24.
Homologues: Orthologues: chimpanzee EHBP1L1 (99% identical), macaque EHBP1L1 (93% identical), pig EHBP1L1 (74% identical), dog EHBP1L1 (71% identical), mouse Ehbp1l1 (69% identical), rat Ehbp1l1 (68% identical), tropical clawed frog ehbp1l1 (34% identical), zebrafish ehbp1l1a (30% identical), Drosophila melanogaster Ehbp1 (20% identical). Paralogues in human: EHBP1 (26% identical), ASPM (12% identical), MICALL2 (9% identical), MICALL1 (9% identical), GAS2L1 (4% identical), SMTNL1 (4% identical), GAS2 (3% identical).
Diseases named in the same sentence as EHBP1L1 in open-access papers:
EHBP1L1 is named in the same sentence as 24 diseases in open-access papers, as found by Europe PMC text mining. Sharing a sentence is not in itself a finding about the gene and the disease. The quoted sentences say what the papers report.
anemia (4 papers, 2022 to 2024). A reduction in the number of red blood cells, the amount of hemoglobin, and/or the volume of packed red blood cells. "While we were analyzing EHBP1L1, EHBP1L1 mutations were discovered in dogs with muscular dystrophy and anemia." (PMID 39445332, 2024). "Homozygous EHBP1L1−/− knockout mice died neonatally and exhibited anemia and shortened small intestinal microvilli at birth." (PMID 36140701, 2022). "Interestingly, EHBP1L1 KO mice died within a few hours after birth due to severe anemia." (PMID 39445332, 2024). "For dogs born prior to the discovery of the causative EHBP1L1 variant, they might well have been euthanized due to anemia and myopathy owing to a lack of effective therapy and poor quality of life." (PMID 39728936, 2024). "Furthermore, EHBP1L1 knockout mice die early and develop severe anemia." (PMID 36011338, 2022).
Dyserythropoietic Anemia (3 papers, 2022 to 2024). "We described a highly damaging EHBP1L1 missense variant associated with congenital dyserythropoietic anemia and polymyopathy in Labrador Retriever littermates." (PMID 36011338, 2022). "This study expands the known genotype–phenotype correlation of EHBP1L1 and the list of potential causative genes in dyserythropoietic anemias and myopathies in humans." (PMID 36140701, 2022). "Here, we describe a highly damaging EHBP1L1 variant associated with dyserythropoietic anemia and polymyopathy in Labrador Retriever littermates." (PMID 36011338, 2022). "Our report of an association of a mutation in the EHBP1L1 gene with congenital dyserythropoietic anemia and polymyopathy provides new insights into the function of this gene and consequences resulting from its loss of function." (PMID 36011338, 2022). "In this study, we further characterize a dyserythropoietic anemia and myopathy syndrome (DAMS) in a large family of ESSP dogs as an autosomal recessive trait that is likely caused by an EHBP1L1 frameshift deletion." (PMID 36140701, 2022). "In addition to the potentially EHBP1L1-related neonatal deaths, EHBP1L1 deficiency is also likely responsible for a unique dyserythropoietic anemia and progressive myopathy syndrome in ESSP dogs, which we term DAMS." (PMID 36140701, 2022). "While the first ESSP dogs with dyserythropoietic anemia and myopathy syndrome (DAMS) and neonatal losses were reported in Scandinavia just a couple of years ago, the herein-reported EHBP1L1 mutant allele frequency among European ESSPs appears surprisingly high." (PMID 39728936, 2024).
renal cell carcinoma (2 papers, 2023). "Herein the authors identify EH domain‐binding protein 1‐like protein 1(EHBP1L1) as a key regulator of immune escape in renal cell carcinoma (RCC)." (PMID 36775874, 2023).
acute kidney injury (1 paper, 2022). Sudden and sustained deterioration of the kidney function characterized by decreased glomerular filtration rate, increased serum creatinine or oliguria. "Six hub genes (MDFI, EHBP1L1, FBXW4, MDM4, RALYL, and ESM1) were identified as potentially predictive of an acute kidney injury." (PMID 36313991, 2022). "The expression of ESM1 and RALYL were markedly increased in control samples, while EHBP1L1, FBXW4, MDFI, and MDM4 were markedly increased in acute kidney injury samples." (PMID 36313991, 2022).
asthma (1 paper, 2022). "EHBP1L1 was positively linked to allograft rejection, asthma, autoimmune thyroid disease, graft–versus–host disease, and type I diabetes mellitus." (PMID 36313991, 2022).
centronuclear myopathy (1 paper, 2022). Centronuclear myopathy (CNM) is an inherited neuromuscular disorder characterized by clinical features of a congenital myopathy and centrally placed nuclei on muscle biopsy. "The pathological changes in the muscle biopsies of the EHBP1L1 variant that the affected Labrador Retrievers were similar to those described for Labrador Retrievers with a centronuclear myopathy caused by mutations in PTPLA and MTM1." (PMID 36011338, 2022). "The connection of EHBP1L1 to BIN1 and DMN2 functions is particularly interesting due to BIN1 and DMN2 mutations being causative in forms of centronuclear myopathy." (PMID 36011338, 2022).
dilated cardiomyopathy (1 paper, 2022). Cardiomyopathy which is characterized by dilation and contractile dysfunction of the left and right ventricles. "Since the clinical signs of skeletal myopathy progressed slowly, dilated cardiomyopathy may be a more subtle and slowly progressing finding or may be associated with other or secondary effects of EHBP1L1 deficiency." (PMID 36140701, 2022). "Interestingly, some affected ESSPs also had evidence of dilated cardiomyopathy, suggesting that cardiac muscle may also be affected by EHBP1L1 deficiency." (PMID 36140701, 2022).
Hypoglycemia (1 paper, 2022). A decreased concentration of glucose in the blood. "Given that neonatal puppies are very sensitive to hypoglycemia, it is possible that EHBP1L1−/− neonates are at increased risk for functional hypoglycemia that is secondary to the dysfunctional regulation of GLUT4 translocation and glucose uptake in the brain, musculature, and fat." (PMID 36140701, 2022).
kidney tumor (1 paper, 2023). "T cells cocultured with EHBP1L1‐deficient primary kidney tumor cells exhibited increased cytotoxicity of CD8+ T cells and more powerful antitumor function." (PMID 36775874, 2023).
microcytic anemia (1 paper, 2022). Anemia in which the red blood cell volume is decreased. "One might speculate that EHBP1L1 deficiency affects the iron metabolism and cellular stability of erythroid cells, but the precise mechanism of the microcytic anemia in dogs with DAMS remains unknown." (PMID 36140701, 2022).
myopia (1 paper, 2022). "Using data derived from GWAS of large consortia, previous reports showed the association of EHBP1L1 with myopia and BP (diastolic BP and mean arterial pressure)." (PMID 35741817, 2022).
Non-immune hydrops fetalis (1 paper, 2021). A type of hydrops fetalis in which there is no identifiable circulating antibody to red blood cell antigens . "Of particular interest is EHBP1L1 because it was independently identified in two families with non-immune hydrops fetalis (NIHF) resulting in recurrent fetal loss." (PMID 34645488, 2021).
otosclerosis (1 paper, 2023). Formation of spongy bone in the labyrinth capsule which can progress toward the stapes (stapedial fixation) or anteriorly toward the cochlea leading to conductive, sensorineural, or mixed hearing loss. "Otosclerosis colocalized genetically with the expression of BANF1, MARK3 and SUPT3H in the highest number of tissues (14, 8 and 6, respectively), while the highest causal posterior probability was observed for TELO2 (9.5%), ZNRD2 (6.3%), EHBP1L1 (6.0%)." (PMID 36653343, 2023).
renal clear cell carcinomas (1 paper, 2022). "EHBP1L1 regulates the CpG methylation of renal cells and was associated with the prognosis of renal clear cell carcinomas." (PMID 36313991, 2022).
myopathy (3 papers, 2022 to 2024). A disease of the muscle in which the muscle fibers do not function properly. "Likewise, the two human fetal deaths related to EHBP1L1 deficiency were not examined for dyserythropoeisis or myopathy." (PMID 36140701, 2022). "EHBP1L1 is an integral part of RAB8 and the BIN1–dynamin complex and could thus readily explain the myopathy." (PMID 36140701, 2022).
tumor (3 papers, 2021 to 2023). "EHBP1L1 depletion significantly inhibits tumor growth, which is attributed to enhanced CD8+ T cell‐mediated antitumor immunity." (PMID 36775874, 2023). "JAK1 overexpression restored PD‐L1 expression in EHBP1L1 knockdown cells, and promoted tumor growth in BALB/c mice." (PMID 36775874, 2023). "This analysis demonstrated distinct differentiation trajectories of CD8+ TIL in tumor microenvironment by EHBP1L1, in which CD8+ T cells infiltrating in EHBP1L1 loss tumors were more likely to differentiate into Teff rather than Tex." (PMID 36775874, 2023). "To better understand the effect of EHBP1L1 expression in tumor cells on CD8+ tumor‐infiltrating lymphocytes (TILs), we performed scRNA‐seq on CD8+ TILs that were FACS‐sorted from shCtrl and shEHBP1L1 Renca tumors." (PMID 36775874, 2023). "To investigate the role of EHBP1L1 in more clinically relevant models, we isolated primary tumor cells from HLA‐A2+ RCC patients." (PMID 36775874, 2023). "Further analysis of the Clinical Proteomic Tumor Analysis Consortium (CPTAC) database indicated that the EHBP1L1 protein level was significantly elevated in ccRCC." (PMID 36775874, 2023). "More importantly, by employing an immunocompetent murine RCC model and an immunodeficient nude mice model, we found that EHBP1L1 depletion significantly inhibited tumor growth and prolonged survival, which was mainly due to the enhanced antitumor immune response." (PMID 36775874, 2023). "Treatment with siRNA effectively knocked down EHBP1L1 in PDX tumor tissues." (PMID 36775874, 2023). "Further analysis showed that although both EHBP1L1 siRNA and anti‐PD‐1 monotherapy inhibited tumor growth and prolonged OS, siEHBP1L1 and PD‐1 blockade combination therapy remarkably reduced tumor burden and improved OS compared to treatment with siEHBP1L1 or anti‐PD‐1 antibody alone." (PMID 36775874, 2023). "Compared to control cells (shCtrl), however, EHBP1L1 deficiency (shEHBP1L1) significantly inhibited Renca‐derived tumor growth in immunocompetent BALB/c mice but not in immunodeficient nude mice." (PMID 36775874, 2023). "Furthermore, IFN-γ signalling can be effectively maintained within tumours through EH domain-binding protein 1-like protein 1 (EHBP1L1) shielding JAK1 from proteasomal degradation." (PMID 37503572, 2023). "Taken together, these results demonstrate that EHBP1L1 enhances the activity of JAK1‐STAT1 signaling to promote the expression of PD‐L1 and thus promotes tumor growth." (PMID 36775874, 2023). "EHBP1L1 interacts with and stabilizes Janus kinase 1 (JAK1), thus significantly inhibiting tumor growth and enhancing anti‐tumor immune response." (PMID 36775874, 2023). "We found that depletion of CD8+ T cells or both CD4+ and CD8+ T cells significantly reversed the tumor regression induced by EHBP1L1 knockdown, whereas depletion of CD4+ T cells alone, had no such effect similar to the IgG control." (PMID 36775874, 2023). "Furthermore, based on a preclinical PDX model with tumor‐specific CD8+ T cell transfer, we confirmed the synergistic effect of the combination of EHBP1L1 inhibition and PD‐1 blockade compared to PD‐1 blockade monotherapy." (PMID 36775874, 2023). "Furthermore, the combination of EHBP1L1 inhibition and ICB reprograms the immunosuppressive TME and prevents tumor immune evasion, thus significantly reinforcing the therapeutic efficacy of ICB in RCC patient‐derived xenograft (PDX) models." (PMID 36775874, 2023). "Although EHBP1L1 expression did not globally alter the composition of immune cells in the TME, further analysis revealed that the expression of EHBP1L1 was positively associated with immune dysfunction score as calculated by tumor immune dysfunction and exclusion (TIDE)." (PMID 36775874, 2023).
cancer (1 paper, 2023). A tumor composed of atypical neoplastic, often pleomorphic cells that invade other tissues. "Collectively, these results suggested that EHBP1L1 may be an attractive therapeutic target for the development of novel cancer therapeutics combined with ICB." (PMID 36775874, 2023). "Taken together, these findings indicate that EHBP1L1 inhibition enhances the therapeutic effects of PD‐1 blockade and may be a potential target for improving cancer immunotherapy efficacy in RCC." (PMID 36775874, 2023). "The combination of EHBP1L1 inhibition and ICB, which reprograms the immunosuppressive TME and prevents immune evasion, represents a potential therapeutic strategy for improving the efficacy of cancer immunotherapy in RCC patients." (PMID 36775874, 2023).
immune dysfunction (1 paper, 2023). "EHBP1L1 expression was associated with immune dysfunction and poor prognosis in TCGA‐KIRC cohort, which was further confirmed by our own RCC patient cohort." (PMID 36775874, 2023).
EHBP1L1 also shares sentences with these, for which no sentence is quoted: autoimmune thyroid disease (1 paper); congenital dyserythropoietic anemia (1); metastatic tumor (1); muscular dystrophy (1); Skeletal myopathy (1); type 1 diabetes mellitus (1).